MYBL2 (MYB proto-oncogene like 2)
Diseases named in the same sentence as MYBL2 in open-access papers (continued):
Sharing a sentence is not in itself a finding about the gene and the disease.
glioma (continued). "The expression level of MYBL2 in different glioma cell lines was detected, and the results showed that MYBL2 is widely expressed in all the examined cell lines, with the greatest expression in U-87 cells." (PMID 30305611, 2018). "Our results show that overexpression of MYBL2 rescued the inhibitory effects of T-96 on cell growth in glioma cells." (PMID 30305611, 2018). "In summary, these results demonstrate that T-96-induced inhibition of proliferation was rescued by overexpression of MYBL2 in glioma cells." (PMID 30305611, 2018). "By analysing the R2 database, we found that glioma patients with higher MYBL2 expression levels showed poorer prognosis." (PMID 30305611, 2018). "Our analysis strongly supports that the role of MYBL2 and FoxM1 in glioma progression and illustrates that increased FoxM1 activity up-regulates MYBL2 through the Akt/FoxM1 signaling cascade." (PMID 28784180, 2017). "In summary, our results suggest that both MYBL2 and FoxM1 over-expression are associated with poor prognosis and EMT in glioma." (PMID 28784180, 2017). "Since our results above indicated the correlation of FoxM1 and MYBL2 in glioma progression, we further study the mechanism of MYBL2 and FoxM1 expression in glioma." (PMID 28784180, 2017). "Both MYBL2 and FoxM1 levels were significantly higher in glioma than in normal tissues, similar to the IHC results." (PMID 28784180, 2017). "We evaluated the effects of MYBL2 and FoxM1 on overall survival of the glioma patients using Kaplan-Meier analysis and log-rank test." (PMID 28784180, 2017). "In the present study, two transcription factors MYBL2 and FoxM1 emerge as synergistic initiators and master regulators of glioma progress and transformation." (PMID 28784180, 2017). "To investigate the functions of MYBL2 and FoxM1 expression in glioma, we up and down regulated both genes in low and high-grade glioma cells." (PMID 28784180, 2017). "We then divided the glioma patients into different groups based on the mean value (3.83) of relative MYBL2 and the mean value (5.88) of relative FoxM1 expression." (PMID 28784180, 2017). "We knocked down of MYBL2 and FoxM1 by siRNA in glioma cells and found that down-regulation of FoxM1 significant reduced MYBL2 protein expression; while down regulation of MYBL2 did a little change of FoxM1 expression." (PMID 28784180, 2017). "To identify the molecular mechanism for the effects of MYBL2 and FoxM1 in glioma progress, we investigated the role of MYBL2 and FoxM1 in cell cycle progression and EMT." (PMID 28784180, 2017). "Our results showed that MYBL2 and FoxM1 were both upregulated in human glioma and influenced tumor progression." (PMID 28784180, 2017). "We performed qRT-PCR analysis and Western blotting to test FoxM1 and MYBL2 expression in high-grade glioma cell lines (U251, U87, U343 and T98G), low-grade cell line (Hs683) and 9 normal tissues." (PMID 28784180, 2017). "Conversely, in high-grade glioma U251 cells, the numbers of colonies were reduced by MYBL2 and FoxM1 knockdown." (PMID 28784180, 2017). "In low-grade glioma Hs683 cells, the numbers of colonies were significantly increased by MYBL2 and FoxM1 over-expressing vector (* p < 0.05)." (PMID 28784180, 2017). "The aim of the present study was to investigate the clinical significance of the correlation between MYBL2 and FoxM1 in glioma and the possible mechanism of FoxM1and MYBL2 expression." (PMID 28784180, 2017). "Meanwhile, MYBL2 closely related to the FoxM1 expression in 79 glioma tissues (r = 0.742, p < 0.05) and LGG (r = 0.83) and HGG (r = 0.74) cohorts of TCGA." (PMID 28784180, 2017). "Here, we have thoroughly investigated the expression levels of MYBL2 in glioma tissues and cell lines." (PMID 28784180, 2017). "We identified both FoxM1 and MYBL2 in high-grade glioma tissues were much higher than in normal brain tissues and low-grade glioma tissues." (PMID 28784180, 2017).
glioma (continued). "In addition to this, it has been shown that MYBL2 is a downstream effector of Akt/FOXM1 signaling in glioma." (PMID 40115748, 2025). "This was verified in the present study, where knockdown of MTDH downregulates MYBL2, suggesting that it may play a role in the treatment of glioma." (PMID 36133745, 2022). "We searched for transcription factors that are positively co-expressed with EIF4EBP1 in gliomas and found EIF4EBP1 mRNA expression to be significantly and positively associated with the mRNA expression levels of MYBL2, FOXM1, ETS1, HIF-1A, JUN, E2F1, and E2F6 in the REMBRANDT dataset." (PMID 35228525, 2022). "So we concluded that MYBL2 is of importance downstream factor of Akt/FoxM1 signaling to stimulate advancement of glioma, and could be considered as a promising gene for molecular targeting therapy and biomarker for radiotherapy of glioma." (PMID 35935338, 2022). "Furthermore, inactivations of Akt/FoxM1 signaling by Akt inhibitor and siRNA-FoxM1 diminish the expression of MYBL2 in glioma cells." (PMID 35935338, 2022). "In conclusion, our work demonstrated that T-96 may inhibit glioma cell growth by regulating the miR-30e-5p/MYBL2 axis in vitro and in vivo." (PMID 30305611, 2018). "In summary, we hypothesise that T-96 suppressed tumour growth by regulating the miR-30e-5p/MYBL2 axis in glioma." (PMID 30305611, 2018). "The present study raises the possibility that FoxM1 and MYBL2 may be potential targets for cancer therapy as both play crucial roles in glioma progression." (PMID 28784180, 2017). "Results showed that whether in low or high-grade glioma, the expression of MYBL2 and FoxM1 are highly correlated (LGG: Pearson’s correlation = 0.83; HGG: Pearson’s correlation = 0.65)." (PMID 28784180, 2017). "Univariate Cox regression analysis indicated that the clinical stage (HR = 1.833, 95% CI: 1.395–2.409, p < 0.001) and high expression of MYBL2 (HR = 3.619, 95% CI: 2.075–6.313, p < 0.001) and FoxM1 (HR = 0.336, 95% CI: 0.187–0.602, p < 0.001) were unfavorable prognostic factor in glioma patients." (PMID 28784180, 2017). "Moreover, more studies are needed to see if the feedback loop of FoxM1 and Akt signaling pathway plays a role in MYBL2 expression in glioma." (PMID 28784180, 2017). "Herein, we demonstrated that if Akt can regulate MYBL2 and FoxM1 expression in glioma cells." (PMID 28784180, 2017). "Furthermore, inactivations of Akt/FoxM1 signaling by Akt inhibitor and siRNA-FoxM1 reduce the expression of MYBL2 in glioma cells." (PMID 28784180, 2017). "In this study, we showed that MYBL2 is interacted with radiotherapy for glioma survival." (PMID 28784180, 2017). "And, we sought to determine whether Akt/FoxM1 signaling pathway is involved in regulating MYBL2 expression and whether these factors can predict the disease progression and prognosis of the glioma patients." (PMID 28784180, 2017). "MYBL2 induction by AKT/FOXM1 signaling was associated with glioma progression and anti-apoptotic mechanisms; however, the AKT inhibitor MK-2206 strongly suppressed MYBL2 in U251 glioma cells and can be a useful drug to tackle the anti-apoptotic mechanisms in glioma based on the AKT-FOXM-MYBL2 axis." (PMID 38835346, 2024). "Among them, high-risk genes MYBL2, C21orf62 and TUBA1C showed higher expression levels in tissues from high-grade gliomas patients (WHO IV grade, GBM), while the expression of low-risk gene KCNIP2 was relatively lower in GBM, which is consistent with our previous hypothesis." (PMID 38577605, 2024). "For example, FOXM1 could elevate the MYBL2 level to promote the progression of human glioma." (PMID 35978634, 2022). "Our results showed that knockdown of MTDH decreased the proliferation rate of glioma cells and increased the rate of apoptosis, while MYBL2 had the opposite effect, indicating that knockdown of MTDH could inhibit the proliferation and increase the apoptosis of glioma cells by downregulating MYBL2." (PMID 36133745, 2022).
glioma (continued). "Overexpression of MYBL2 could reverse the knockdown effects of MTDH in glioma cells." (PMID 36133745, 2022). "Whether MTDH positively regulates MYBL2 in glioma cells needs further study." (PMID 36133745, 2022). "It was speculated that T-96 might arrest the cell cycle by downregulating MYBL2 in glioma cells." (PMID 30305611, 2018). "MYBL2 is a key downstream factor of Akt/FoxM1 signaling to promote progression of human glioma, and could be a new candidate gene for molecular targeting therapy and biomarker for radiotherapy of glioma." (PMID 28784180, 2017). "The identification of MYBL2, RBM6, VEPH1, AHNAK2, GNG10, and DUSP14 as key genes offers valuable insights into the molecular mechanisms underpinning glioma progression and its interaction with COVID-19." (PMID 39684661, 2024). "The results of cell biology assays demonstrated that knockdown of MYBL2 or TUBA1C markedly inhibited the proliferation; and migration of glioma cells." (PMID 38577605, 2024). "Down regulation of FoxM1 and MYBL2 by siRNAs induced the cell cycle blocking, apoptosis and EMT (Epithelial-mesenchymal transition) of glioma cells." (PMID 35935338, 2022). "Taken together with inhibition studies aiming the Akt/FOXM1 signaling, these results propose that transcription factor MYBL2 functions as a key downstream component of the Akt/FOXM1 axis, promoting the progression of gliomas." (PMID 35409080, 2022). "This study showed that MTDH and MYBL2 were overexpressed in gliomas, and knockdown of MTDH inhibited the expression of MYBL2." (PMID 36133745, 2022). "The present study showed that knockdown of MTDH inhibits glioma proliferation and migration and promotes apoptosis by downregulating MYBL2, which suggests that MTDH is a potential gene in clinical treatment of glioma." (PMID 36133745, 2022). "Recent studies have demonstrated that low expression of MYBL2 induces cell cycle arrest, apoptosis, and epithelial–mesenchymal transition (EMT) in glioma cells, and it is positively regulated by FoxM1, a member of the forkhead box transcription factor family." (PMID 36133745, 2022). "In this study, we explored the function of MTDH in glioma cells and found that MTDH and MYBL2 were highly expressed in glioma tissues based on the analysis of the GEPIA website." (PMID 36133745, 2022). "Therefore, knocking down MTDH and targeting MYBL2 may provide new insights for glioma therapy." (PMID 36133745, 2022). "The upregulation of CCNB1, CDK1, CXCL8, IGFBP3, MYBL2, SERPINE1 also notably indicated poor overall survival of glioma patients (HR>1, P=0.000<0.05)." (PMID 34512164, 2021). "Down regulation of FoxM1 and MYBL2 by siRNAs induced the cell cycle arrest, apoptosis and EMT of glioma cells." (PMID 28784180, 2017). "In this study, we found that MYBL2 and TUBA1C, highly expressed in high-grade gliomas, may be involved in the process of PANoptosis and promoted the proliferation and migration of glioma cells." (PMID 38577605, 2024). "The roles of MYBL2 and TUBA1C on tumor progression were investigated in glioma cells." (PMID 38577605, 2024). "Four PANoptosis-related predictors (MYBL2, TUBA1C, C21orf62 and KCNIP2) were identified and predictive PANRG score model was developed for glioma based on bulk-seq and scRNA-seq analysis, which is significantly associated with tumor immune landscape and therapeutic responses." (PMID 38577605, 2024). "Overall, MYBL2 and TUBA1C promoted proliferation and migration, which may play an important role on glioma progression." (PMID 38577605, 2024). "MYBL2 (MYB Proto‐Oncogene Like 2) is a member of the MYB family of TF genes, is a key downstream factor of AKT/FOXM1 signalling to promote progression of human glioma." (PMID 32696617, 2020). "Besides, we also confirmed the biological functions of two oncogenic predictors (MYBL2 and TUBA1C) by cell experiments, which revealed that knockdown of MYBL2 or TUBA1C could significantly inhibit the proliferation and migration of glioma cells." (PMID 38577605, 2024).
glioma (continued). "MYBL2 regulates cell cycle, apoptosis, and epithelial-to-mesenchymal transition (EMT), and is overexpressed in leukemia and several solid tumors (e.g., breast, lung, colorectal and gallbladder cancer, hepatocellular and esophageal squamous cell carcinoma, glioma, and neuroblastoma)." (PMID 38835346, 2024). "The biological significance of two panoptosis-related predictors, MYB proto-oncogene like 2 (MYBL2) and tubulin alpha-1C chain (TUBA1C), was also confirmed by the experimental knockdown of both predictors, which resulted in a significant inhibition of glioma cell proliferation and migration." (PMID 39062119, 2024). "Finally, cell migration and invasion assay results showed that knockdown of MTDH reduced the ability of glioma cells to invade and migrate, while MYBL2 was able to reverse this inhibition, indicating that knockdown of MTDH inhibited glioma cell migration and migration by downregulating MYBL2." (PMID 36133745, 2022). "However, it is still not clear about the role of the MYBL2 gene in glioma." (PMID 28784180, 2017). "This demonstrated a significant overexpression of MYBL2, FOXM1, ETS1, HIF-1A, and JUN in both glioma cohorts compared to non-neoplastic brain tissues." (PMID 35228525, 2022).
ovarian carcinoma (21 papers, 2003 to 2026). A malignant neoplasm originating from the surface ovarian epithelium. "We found tumor derived MYBL2 indicated poor prognosis and selectively correlated with tumor associated macrophages (TAMs) in ovarian cancer." (PMID 37865750, 2023). "To delve deeper into the functional significance of MYBL2 in ovarian cancer cell lines, we delved into the repercussions of MYBL2 knockdown on two particular cell lines, namely SK-OV-3 and A2780." (PMID 39136009, 2024). "Future investigations should involve multicenter studies with larger sample sizes to validate the roles of MYBL2 and the TOP2A TCs Risk Score in ovarian cancer." (PMID 39136009, 2024). "This study provided experimental evidence that the inhibition of MYBL2 through knockdown significantly suppresses the proliferation and migratory capacity of ovarian cancer cells." (PMID 39136009, 2024). "MYBL2 wielded a momentous influence on the proliferation and migration of ovarian cancer cell lines." (PMID 39136009, 2024). "We have revealed the heightened susceptibility of the C2 TOP2A+ TCs subgroup to neoadjuvant chemotherapy and emphasized the role of MYBL2 within the C2 subgroup in promoting the occurrence and progression of ovarian cancer." (PMID 39136009, 2024). "In ovarian cancer cells, MYBL2 was shown to serve as an upstream transcription factor to CDCA8, directly increasing its expression to alter cell cycle regulation and DNA repair." (PMID 37509213, 2023). "As previously reported, the transcription factor CENPA mediates an important role for MYBL2 in ovarian cancer cell proliferation." (PMID 36601328, 2022). "HNF1B and MYBL2 were also reported to be down regulated in renal cell carcinoma, ovarian cancer and myeloid malignancies." (PMID 31795960, 2019). "In line with this is that MYBL2 is located on a chromosomal area (20q) recently identified by in silico chromosomal clustering of genes displaying altered expression patterns in ovarian cancer." (PMID 27542596, 2016). "In addition, knockdown of MYBL2 significantly inhibited the proliferation and migration of ovarian cancer cells." (PMID 41491570, 2026). "Therefore, it can be concluded that MYBL2 knockdown significantly suppresses the proliferation and migration abilities of ovarian cancer cells." (PMID 39136009, 2024). "Moreover, the transcription factor MYBL2 in this subgroup played a critical role in ovarian cancer development." (PMID 39136009, 2024). "Meanwhile, MYBL2 overexpression has been observed in cancers such as bladder cancer and prostate cancer, and it is currently used as a biomarker for poor prognosis in ovarian carcinoma." (PMID 37840753, 2023). "However, the specific biological functions of MYBL2 in ovarian cancer remain to be elucidated." (PMID 39136009, 2024). "The results showed that MYBL2 in C2 TOP2A + TC subgroup was involved in the development and progression of ovarian cancer." (PMID 39136009, 2024). "Despite the lack of a significant correlation between RAD54L expression and overall survival, higher MYBL2 and RAD54L expression tended to predict a worse prognosis in patients with ovarian cancer." (PMID 38424195, 2024). "Therefore, MYBL2 could be a promising focus in relation to ovarian cancer." (PMID 39136009, 2024). "The MYBL2/CCL2 axis contributing to TAMs recruitment and M2-like polarization is crucial to immune evasion and anti-PD-1 resistance in ovarian cancer, which is a potential target to enhance the efficacy of immunotherapy." (PMID 37865750, 2023). "For example, as an upstream transcription factor of CDCA8, MYBL2 promotes CDCA8 expression and hence improves the sensitivity of ovarian cancer cells to olaparib and DDP." (PMID 37840753, 2023). "Moreover, E2F1 transcriptionally regulates the expression of the oncogenes MYBL2 and RAD54L, driving ovarian cancer progression." (PMID 38424195, 2024).
ovarian carcinoma (continued). "Further research efforts should focus on validating the roles of MYBL2 and the TTRS in larger cohort studies while integrating complementary proteomic and metabolomic approaches to gain a more comprehensive understanding of ovarian cancer biology." (PMID 39136009, 2024). "While the role of MYBL2 in ovarian cancer and derived entities is not well established, our data would indicate that it acts similarly in PC of ovarian cancer origin." (PMID 27542596, 2016). "NSUN2 is aberrantly upregulated in ovarian cancer and promotes the malignancy of ovarian cancer through regulating the expression of the oncogenic driver E2F transcription factor 1 (E2F1) in an m5C-dependent manner, and E2F1 facilitates the transcription of NSUN2 as well as MYBL2 and RAD54L." (PMID 38424195, 2024).